CRP (C-reactive protein)
Diseases named in the same sentence as CRP in open-access papers (continued):
Sharing a sentence is not in itself a finding about the gene and the disease.
Obesity (continued). "For example, obesity was characterized by systemic low-grade chronic inflammation, marked by elevated levels of CRP, IL-6, IL-8, and tumor necrosis factor-α (TNF-α) in the serum." (PMID 40612555, 2025). "Inflammatory markers known as CRP, leptin, adiponectin, and the neutrophil/lymphocyte ratio have shown significant correlations with disorders related to obesity." (PMID 40282897, 2025). "Obesity is strongly correlated with inflammatory biomarkers, such as CRP, interleukin‐6 (IL‐6), and tumor necrosis factor‐alpha (TNF‐α), both IL‐6 and TNF‐α are produced by adipocytes and act as adipokines and inflammatory markers." (PMID 40551726, 2025). "Researchers found that individuals with severe obesity had higher levels of proinflammatory markers such as CRP and IL-6, oxidized LDL, and worse thickness and stiffness in vessels." (PMID 40703531, 2025). "Several phenotypic responses observed in pigs closely mirror those described in humans, such as the increase in circulating HDL following a MUFA-rich diet or even the rise in CRP levels, which is particularly pronounced in females with obesity." (PMID 41327907, 2025). "There is a scarcity of research on how CRP affects the relationship between dietary patterns and obesity in children." (PMID 39599620, 2024). "Both CRP and C3 are acute phase reactants mainly produced in the liver, though in obesity, the excess of these proinflammatory cytokines will promote an increased synthesis of CRP and C3 in adipose tissue." (PMID 39061938, 2024). "Our study showed a statistically significant difference in the prediction of mortality and severity using G/L ratio, PCT ferritin, CRP level, age, and obesity." (PMID 38793085, 2024). "Notably, a supplement containing glucomannan, inulin, psyllium, and apple fiber was most effective in reducing BMI, body weight, and CRP levels, suggesting that dietary fiber supplements could enhance weight loss and positively impact metabolic health in individuals with obesity and overweight." (PMID 38398881, 2024). "Children with obesity or overweight had lower vitamin D levels, increased blood pressure, visceral and subcutaneous fat thickness, and higher leukocytes, C-reactive protein, and myeloperoxidase levels." (PMID 39408928, 2024). "In addition to CRP, other acute-phase proteins, such as the proinflammatory adipokine serum amyloid A, could also play a critical role in obesity-associated inflammation and in obesity-related complications, including AF." (PMID 38247541, 2024). "When looking at the different components of the disease activity scores, participants with obesity had not only higher patients’ and physicians’ assessments scores but also higher tender joint counts and CRP values compared with participants with lower BMI." (PMID 38580350, 2024). "Inflammatory biomarkers of CRP areknown to predict worseoutcomes in cardiovascular and chronic diseases.Various factors such as fluid retention, oxidative stress, obesity, smoking, andgenetic factors contribute to this inflammation." (PMID 39076541, 2024). "Subgroup analyses revealed a substantial decline in serum CRP levels among healthy and unhealthy participants with obesity and baseline serum CRP levels >3 mg/L in long-term (≥12 weeks) supplementation with high doses of SIL." (PMID 38671838, 2024). "Elevated systemic pro-inflammatory markers like C-reactive protein, TNF-α, TGF-β, leptin, and IL-6 are linked to the obesity." (PMID 38762465, 2024). "More than 50% of PCOS patients are overweight or obese, while obesity induces adipotoxicity, leading to the release of large amounts of cytokines (serum C-reactive protein [CRP], TNF-α and IL-6) and adipokines into the systemic circulation and ovaries." (PMID 38212789, 2024). "This is because circulating levels of pro‐inflammatory cytokines, such as interleukin (IL)‐1β and C‐reactive protein (CRP), are increased in individuals with obesity." (PMID 39107107, 2024).
Obesity (continued). "Patients with obesity showed elevated levels of circulating ferritin, C-reactive protein (CRP), and tumor necrosis factor-a (TNF-a) upon admission." (PMID 39057109, 2024). "The clinical literature highlights the association between obesity, inflammation, and hypercoagulability, with shortened APTT and elevated CRP levels linked to increased thrombotic risk." (PMID 39770957, 2024). "Herein, we observed that laboratory evidence of inflammation (i.e., CRP), insulin resistance (i.e., increased TG-HDL ratio) and elevated BMI (i.e., overweight/obesity) are highly associated with cognitive impairment in individuals with PCC." (PMID 38424537, 2024). "It is expected that targeting the disruption of pathways mediated by FVC, FEV1, CRP, and IL-6 can reduce the adverse impact of obesity on acute bronchitis and pneumonia, thereby alleviating the burden of LRTIs." (PMID 39337223, 2024). "Significantly, obesity, neuropathy, complications, peripheral blood CRP concentrations, female sex, and social support emerged with suggestive evidence." (PMID 38617916, 2024). "CRP levels are increased in people with obesity compared with their normal weight counterparts, and in cancer patients compared with healthy controls or patients with benign diseases." (PMID 38914635, 2024). "Both obesity and cigarette smoking increase concentrations of the proinflammatory C-reactive protein (CRP), whereas high dietary intakes of vitamin C appear to decrease it." (PMID 38666038, 2024). "The MetS component, such as obesity, can promote inflammation and elevate CRP by secreting pro-inflammatory adipokines; also, CRP can increase insulin resistance and hyperglycemia by interfering with insulin signalling." (PMID 38243159, 2024). "In terms of significant fibrosis, the variables that were associated in univariate analysis in SLE patients were BMI, waist circumference, obesity, triglycerides, high-density cholesterol, low-density cholesterol, C4 levels, and C-reactive protein." (PMID 38902318, 2024). "The present study highlights a significant reduction in CRP levels in participants with AIDs, suggesting the possible role of diet in reducing the systemic inflammation that accompanies obesity." (PMID 39356960, 2024). "In that study, (18F) NaF uptake significantly correlated with age, male gender, obesity, fibrinogen, and CRP compared to healthy controls." (PMID 38248862, 2024). "In general, obesity is characterized by elevated serum CRP levels, as these levels show a positive correlation with adipocyte hypertrophy." (PMID 38674875, 2024). "CRP can be confounded by various factors such as obesity, smoking, low vitamin D levels, low physical activity, inappropriate diet, allergy, stress, sleep disturbances and subclinical infections which were not completely controlled in our study." (PMID 39039500, 2024). "Future studies should investigate the relationship between CRP and BC in patients with obesity on a larger scale." (PMID 38914635, 2024). "Participants with obesity at baseline also had less reduction in swollen and tender joint counts, CRP and assessment scores of disease activity and pain after treatment initiation compared with the rest of the cohort." (PMID 38580350, 2024). "In fact, in obesity patients with NAFLD, SCGF-β levels have been linked to insulin resistance and hepatic steatosis severity with the mediation role of CRP." (PMID 38469144, 2024). "Increased inflammatory cytokines such as interleukin 6 and tumor necrosis factor alpha (TNFα) are hallmarks of obesity, and promote the secretion of hepatic C-reactive protein (CRP) which further induces systematic inflammation." (PMID 38742193, 2024). "For example, in a fibromyalgia cohort, symptoms were worse in those with higher CRP, which was explained mostly by obesity and physical inactivity despite the prevailing theory that myalgia symptoms are not primarily caused by inflammation." (PMID 38786992, 2024).
Obesity (continued). "Previous studies have observed higher concentrations of inflammatory markers such as CRP, interleukin-6, leptin, and hepcidin in women with obesity compared with normal weight." (PMID 39255312, 2024). "We observed higher means for TC (≥ 190mg/dL), HOMA-IR (≥ 2.71), andhs-CRP (≥ 1mg/L) in individuals with the obesity and SO phenotypes." (PMID 38896593, 2024). "In our study, we found higher median CRP concentrations in women and men with obesity than in those with normal weight." (PMID 39769504, 2024). "CRP, IL-6, and FEV1 play crucial intermediary roles in the association of obesity with pneumonia, and CRP, FVC, and FEV1 mediate the effect of obesity on acute bronchitis." (PMID 39337223, 2024). "These miRNA concentrations correlated significantly with body mass index including percent fat mass, waist and regional fat distribution and other obesity measures as well as laboratory parameters like adiponectin, C-reactive protein and lipids." (PMID 38541185, 2024). "The variables selected for their score from the multivariate analysis included sex (male), constipation, not using proton pump inhibitor medication, Hb levels below 11.9 g/L, CRP levels above 80 mg/L, and obesity (BMI > 30)." (PMID 39404869, 2024). "Underlying hypoxemia in OS (originating from OSA, obesity, and COPD) induces the release of systemic inflammatory mediators including C-reactive protein, interleukin-6 and 8, tumor necrosis factor-alpha, and reactive oxygen species." (PMID 39585008, 2024). "In obese asthmatic rats, the degree of airway inflammation is higher, accompanied by elevated CRP levels, indicating a synergic impact of obesity on pre-existing airway inflammation." (PMID 39201554, 2024). "Therefore, we speculate that the association of CRP with knee pain is mediated through obesity." (PMID 39222043, 2024). "List of SNPs associated with Obesity, HTN, and DLP, HDL and CRP at a significance level of 10−5, with their corresponding minor allele, MAF, chromosome (Chr)." (PMID 39717478, 2024). "We identified four factors, FEV1, FVC, CRP, and IL-6, that mediated the effects of obesity on LRTIs." (PMID 39337223, 2024). "First, naps >30 min increase nocturnal sleep fragmentation and the frequency of awakenings, leading to elevated IL-6 and CRP levels, which then increase the risks of inflammation and obesity." (PMID 38590820, 2024). "Obesity CLGI is traditionally defined based on the concentration of highly sensitive C-reactive protein (hs-CRP)." (PMID 39336564, 2024). "A multiple linear regression was run to predict ESSDAI according to obesity, steroid treatment, statin treatment, anti-Ro/SS-A+, anti-La/SS-B+, rheumatoid factor+, CRP (mg/L), LDH (U/L), triglyceride (mmol/L) and cholesterol (mmol/L)." (PMID 39682633, 2024). "The association of obesity with a worse DAS course is mainly present in ACPA-positive RA; especially SJC and CRP levels remain higher in ACPA-positive RA patients with obesity but not ACPA-negative RA patients." (PMID 38321544, 2024). "Excess macronutrients and the accumulation of fatty acids in obesity lead to adipose tissue triggering the production of C-reactive protein (CRP) and proinflammatory cytokines." (PMID 38398880, 2024). "Semaglutide notably lowered ALT and C-reactive protein levels involving individuals with type 2 diabetes and/or obesity." (PMID 39286709, 2024). "Our study is one of the few to assess CRP levels in people with obesity and compare them to those in people with normal weight." (PMID 39769504, 2024). "Our study has demonstrated that the granulocyte-to-lymphocyte (G/L) ratio, CRP, ferritin, procalcitonin, age, and obesity can collectively serve as economic, rapid, and reliable markers for predicting in-hospital mortality." (PMID 38793085, 2024). "CRP was the most frequently reported inflammation marker in the reviewed papers and levels aligned with obesity-related inflammation." (PMID 39324337, 2024).
Obesity (continued). "For both men and women, participants with hs-CRP greater than 3 mg/L were older, more likely to have obesity and abdominal obesity, more likely to be married, and had lower levels of education (all, p < 0.0001)." (PMID 38542799, 2024). "Our results highlight the overexpression of TNFα and IL-1β in the obesity group, while the CRP was significantly higher on the obesity group compared to the controls; this correlates with the elevated BMI and low plasma iron distribution in the obese patients." (PMID 39057082, 2024). "Obesity is associated with a low grade inflammatory state, which may be triggered by adipocyte hypertrophy and consequent secretion of pro-inflammatory markers, including interleukin (IL)-6, IL-8, IL-1β, C-reactive protein (CRP), tumour necrosis factor-α (TNF-α) and monocyte chemoattractant factor." (PMID 38472359, 2024). "Obesity is associated with a chronic, low-grade inflammatory state, characterized by elevated levels of pro-inflammatory cytokines such as TNF-α, IL-6, and CRP." (PMID 39468643, 2024). "The acute phase protein CRP is a marker of inflammation and is increased in humans with obesity, suggesting possible subclinical inflammation." (PMID 39296580, 2024). "Numerous studies have shown a strong correlation between elevated CRP levels and various diseases, including but not limited to cardiovascular diseases, diabetes, and obesity." (PMID 38933362, 2024). "Chronic inflammation is a biological feature of aging and is increased in obesity, with biomarkers such as C-reactive protein (CRP), interleukin-1B/6, and tumor necrosis factor-alpha (TNF-α) increasing with age." (PMID 39339652, 2024). "Prior studies have shown a positive correlation between obesity and the level of high sensitive C-reactive protein (hs-CRP)." (PMID 38685027, 2024). "W-BC has been shown to decrease CRP and proinflammatory cytokines IL-6 and resistin, while increasing the anti-inflammatory cytokine IL-10 in men with obesity." (PMID 39576692, 2024). "As observed in our research, the CRP value was significantly higher in patients with obesity compared to controls with a normal value of BMI." (PMID 39081789, 2024). "A recent study attempting to better define specific physiologic connections between obesity and inflammation used a mouse model with a CRP transgene." (PMID 38978699, 2024). "In obesity, visceral fat tissue releases proinflammatory cytokines into the portal vein, directly triggering CRP production and boosting an oxidative stress response in the liver." (PMID 38255379, 2024). "This study illuminates crucial connections between ethnicity, dietary patterns, and key inflammatory biomarkers, i.e., WBCs and CRP, in the context of obesity." (PMID 38398880, 2024). "Some of these factors, including age, socioeconomic status, hypertension, diabetes mellitus, and obesity, affect both the occurrence of preeclampsia and CRP levels." (PMID 38672972, 2024). "Obesity is a low-grade inflammation that is presented by elevated concentrations of circulating cytokines such as C-reactive protein, tumor necrosis factor-α) and interleukins such as IL-6." (PMID 38243194, 2024). "The increased CRP values and airway hyperresponsiveness to the methacholine challenge suggest a synergistic effect of obesity on amplifying the existing inflammation induced by asthma." (PMID 39201554, 2024). "In patients with elevated CRP levels (>10 mg/L) or low albumin levels (<35 g/L), obesity was found to have a protective effect on survival." (PMID 39795603, 2024). "Single logistic regression showed that logTSH, low ferritin status, high CRP, high IL-6, obesity as well as low hCG concentrations and increasing age were all significantly associated with IH." (PMID 38330593, 2024). "Alongside possible reduced iron absorption, some inflammatory markers are reported to be increased in obesity including C-reactive protein (CRP), IL-6, and ferritin." (PMID 39236809, 2024).
Obesity (continued). "CRP is a liver-synthesized protein that increases during inflammation and is elevated in individuals with obesity due to higher adipose tissue levels." (PMID 39770957, 2024). "Numerous studies consistently show that individuals with obesity exhibit higher CRP levels—a marker of low-grade inflammation—compared to those with a healthy weight." (PMID 39717478, 2024). "Our comprehensive analysis demonstrated that obesity, neuropathy, complications, peripheral blood CRP concentrations, female sex, and social support are robust risk factors for mental health disorders in this population." (PMID 38617916, 2024). "Obesity-related inflammation is linked to pro-inflammatory cytokines such as TNF-α, IL-6, uric acid, and CRP, which interfere with normal GnRH secretion from the hypothalamus and reduce testosterone production." (PMID 39473678, 2024). "TNF-α also has a positive correlation with obesity and modulates leptin, as well as stimulates the production of IL-6 and CRP." (PMID 38734032, 2024). "Obesity causes adipocytes to secrete a variety of inflammatory factors, including tumor necrosis factor-α (TNF-α), interleukin-6 (IL-6), and C-reactive protein (CRP)." (PMID 38707891, 2024). "Our data showed that G/L ratio leucocytes, ferritin and CRP level, age, and obesity (p < 0.0001) have a stronger relevance to outcome compared to PCT (p < 0.0002)." (PMID 38793085, 2024). "Primarily produced by the liver, CRP is also synthesized in patients with obesity in response to inflammatory mediators, mainly interleukin-6 (IL-6)." (PMID 39141186, 2024). "The DASH diet has been shown to effectively reduce obesity-related markers of inflammation, such as hs-CRP levels, compared to usual diets." (PMID 38476230, 2024). "When looking at different markers of disease activity from week 8 to week 48, higher tender joint counts, CRP and assessment scores of disease activity and pain were observed in participants with obesity compared with the rest of the cohort." (PMID 38580350, 2024). "White blood cell count, hematocrit, thrombocyte, potassium, glucose, uric acid, triglyceride, ALAT/GPT, GGT, alkaline phosphatase, and CRP values were significantly higher in patients with obesity compared to controls with a normal BMI range." (PMID 39081789, 2024). "A 2018 systematic review found that obesity stigma is positively linked to various health indicators, including conditions such as obesity itself and diabetes, as well as physiological markers like cortisol and C-reactive protein level and oxidative stress." (PMID 38613032, 2024). "The odds ratio for those with obesity compared with normal to knee pain was 2.27 (1.42−3.65) in the first quartile of CRP, 1.99 (1.38−2.86) in the second, 2.15 (1.38−3.33) in the third, and 2.92 (1.72−4.97) in the fourth." (PMID 39222043, 2024). "Log-hs-CRP levels, self-reported family history of obesity, and total fat intake were also related to serum levels (p < 0.1)." (PMID 39079151, 2024). "This supports earlier findings showing that in individuals with obesity, adipose tissue dysfunction is a key factor contributing to low-grade inflammation, as indicated by elevated concentrations of CRP and IL-6." (PMID 36462595, 2023). "Both obesity and OSA are directly associated with elevated levels of inflammatory markers, including C-reactive protein (CRP) and interleukin (IL)-6, substantially increasing the risk of cardiovascular disease." (PMID 37834123, 2023). "Instead, decreases in BMI, TNF-α, IL-6, and CRP, most of them significant, were reported in the reports by Moore on the population with overweight or obesity." (PMID 37885010, 2023). "Individuals with obesity also exhibited elevated levels of leptin, C-reactive protein, insulin, and HOMA-IR index." (PMID 37049393, 2023).